CD276 (CD276 molecule)
Diseases named in the same sentence as CD276 in open-access papers (continued):
Sharing a sentence is not in itself a finding about the gene and the disease.
melanoma (91 papers, 2013 to 2026). A malignant, usually aggressive tumor composed of atypical, neoplastic melanocytes. "Notably, CD276 emerged as a selective surface marker, uniquely characterizing melanoma exosomes and presenting a compelling target for diagnostic stratification and therapeutic intervention." (PMID 40805206, 2025). "To address this problem, we designed a bivalent tandem CAR (TanCAR) targeted two pan-tumor-associated antigens, CD70 and B7-H3 (CD276), which could also apply for the immunotherapy of multiple types of solid tumor and melanoma." (PMID 32685008, 2020). "CD26 (DPP4) and CALR are involved in immune modulation and cell signaling, while B7-H3 (CD276) is a prominent immune checkpoint molecule highly expressed in melanoma and other tumors, contributing to immunosuppression and tumor progression." (PMID 40805206, 2025). "For example, CAFs from renal, colon, and lung cancers or melanoma can express programmed PD-L1, PD-L2, or CD276 (also known as B7-H3), with potential participation in T cell exhaustion." (PMID 36338519, 2022). "It was already shown in multiple studies that CD276 is aberrantly expressed in malign melanoma and the present study demonstrated CD276 abundance in all examined melanoma cell lines." (PMID 33925968, 2021). "Here, we showed that CD276-CAR NK-92 cells demonstrated successful eradication of various melanoma cell lines in vitro in 2D as well as 3D experiments." (PMID 33925968, 2021). "Current research shows that CD276 expression is elevated in most tumors, including melanoma and lung cancer, and is closely related to the inhibition of T-cell response and immune evasion of tumors." (PMID 34298996, 2021). "CD276-CAR NK-92 cells as well as parental NK-92 cells were co-incubated with calcein-labeled melanoma cells." (PMID 33925968, 2021). "All melanoma cell lines that were screened during this study showed uniform abundance of CD276 expression." (PMID 33925968, 2021). "All melanoma spheroids that were co-incubated with CD276-CAR NK-92 cells were completely eradicated after 48 to 72 h." (PMID 33925968, 2021). "Compared to parental NK-92 cells, co-incubation of CD276-CAR NK-92 cells with melanoma cells significantly increased secretion of various interleukins, among others, IL-6 (98- to 317-fold) and IL-10 (6- to 15-fold)." (PMID 33925968, 2021). "Research has confirmed the expression of CD276 in primary and metastatic melanoma as well as its significant role in the progression of melanoma and events of metastasis." (PMID 33869027, 2021). "In tumors, CD276 or B7-H3 is reported to be highly expressed in tumors of various tissue types including melanoma, which is closely related to the poor clinical outcome of tumor patients." (PMID 34335689, 2021). "In order to examine the kinetics of CAR-mediated cytolysis, CD276-CAR NK-92 as well as untransduced NK-92 cells were co-incubated with unlabeled melanoma cells and monitored using the xCELLigence real-time cell analysis (RTCA) system." (PMID 33925968, 2021). "Next, the melanoma cell lines were used as target cells in standard calcein release assays (CRA) to assess the specific cytotoxic potential of CD276-CAR NK-92 cells." (PMID 33925968, 2021). "Furthermore, in 2D or 3D in vitro experiments, CAR NK-92 cells effectively target CD276 (B7-H3), which is highly expressed in melanoma cells." (PMID 38057843, 2023). "The knock-down of CD276 expression in melanoma cells decreased their metastatic potential." (PMID 35563359, 2022). "The ability of melanoma cells to invade the gel decreases by silencing CD276 using shRNA." (PMID 33842369, 2021).
melanoma (continued). "Moreover, CD276 (B7-H3), which is highly expressed on melanoma, is efficiently targeted by CAR NK-92 cells when tested in 2D or 3D in vitro settings." (PMID 34572949, 2021). "Importantly, CD276 is overexpressed in a variety of solid tumors, including melanoma." (PMID 33925968, 2021). "Therefore, three-dimensional melanoma spheroid models were established to examine whether CD276-CAR NK-92 prove to be as effective in tumor cell lysis as in a standard CRA." (PMID 33925968, 2021). "Additionally, flow cytometric analysis showed no increase in surface expression of two important pathways in NK-mediated apoptosis induction, Fas ligand (FasL) and TNF-related apoptosis-inducing ligand (TRAIL), in CD276-CAR NK-92 cells upon co-incubation with melanoma cells." (PMID 33925968, 2021). "B7-H3 (CD276), MIC-1, and ICAM1, however, were detectable and present in all three melanoma exosomes." (PMID 40805206, 2025). "Melanoma cells overexpress the protein biomarkers midkine (MDK) and CD276 (B7-H3), which appear to have increased expression during malignancy." (PMID 41463631, 2025). "Specifically, PD-L1 (CD274) mRNA was detected in melanoma cells, along with CD40 and B7-H3 (CD276) mRNAs." (PMID 40647495, 2025). "As a methodology, SFD is able to reveal well-known proteins in melanoma exosomes that are immune-related and are also surface-expressed proteins, such as CD26 (DPP4), CD44, CALR, B7-H3 (CD276), CSF1, ICAM1, L1CAM, MICB, APOH, TIMP1, and CD39." (PMID 40805206, 2025). "Previous CAR NK cell therapies against melanoma have targeted GPA7 and CD276 (B7-H3) using NK-92 as the NK cell source." (PMID 36434591, 2022). "Next, a cytokine secretion profile for CD276-CAR and parental NK-92 cells upon co-incubation with melanoma cells was established to screen for the release of NK effector molecules." (PMID 33925968, 2021). "CD276-CAR and NK-92 cells were subsequently incubated in tumor cell supernatant for 48 h and used as effector cells in a CRA with all three melanoma cell lines." (PMID 33925968, 2021). "We found no significant decrease in cytotoxicity against all three melanoma cell lines at any E:T ratio, which suggests that TGFβ seems to have no negative effect on CD276-CAR NK-92-mediated tumor lysis." (PMID 33925968, 2021). "Additionally, CD276-specific chimeric antigen receptors have been developed and tested as CAR-engineered T cells in multiple pre-clinical studies targeting various solid tumors including melanoma." (PMID 33925968, 2021). "Incubation of CD276-CAR NK-92 cells in supernatant from FM-3 culture did not impact cytotoxicity while CAR NK-92 cells incubated with Mel-Juso as well as WM115 cell culture supernatant did show slightly decreased CAR-mediated cytolysis of all three melanoma cell lines." (PMID 33925968, 2021).
lung cancer (86 papers, 2011 to 2026). A malignant neoplasm involving the lung. "Research on several antigens, including c-MET, DLL3, FAP, and B7-H3 (CD276), has been conducted concerning lung cancer treatment." (PMID 38694508, 2024). "As a key member of the B7 superfamily, CD276 is highly expressed in hepatocellular carcinoma, lung cancer, and adrenocortical carcinoma." (PMID 37428291, 2023). "CD276 expression on lung cancer leads to a lower number of tumor infiltrating lymphocytes and promotes lymph node metastasis, suggesting a role for CD276 in immune evasion and tumor progression." (PMID 36973475, 2023). "Silencing CD276 in human lung cancer cells inhibited cellular invasion, mitosis, and migration by integrin-dependent mechanisms." (PMID 35563359, 2022). "CD276, also known as B7 homolog 3 protein (B7-H3), is overexpressed in tumor cells and contributes to the development of lung cancer." (PMID 36699466, 2022). "Research on CD276 has progressed mainly regarding the lung cancer subtype; however, more clinical trials and animal models that allow the application of anti-CD276 mAbs are warranted to evaluate its efficacy and safety." (PMID 34367975, 2021). "Next, we assessed SMARCAL1 and CD276 expression in lung cancer cell lines PC9 and HCC827." (PMID 39994264, 2025). "CD276 (or B7-H3) is also being targeted in the lung cancer CAR-T clinical landscape." (PMID 35455052, 2022). "For example, CD276 (ENSG00000103855) only been shown in the rules of lung cancer cell lines." (PMID 34917619, 2021). "Although CD276 is highly expressed in a variety of tumors, and its molecular mechanism to promote cancer progression is not clear, our results show that it may be more important for lung cancer." (PMID 34917619, 2021). "In other forms of lung cancer, we showed a heterogeneity of blood CTCs and CSCs populations, as well as changes in other cell populations (ALDH+, CD87+CD276+, and EGF+Axl+) in smokers." (PMID 36142766, 2022). "CD44, CD87, CD117, CD276, Axl, EGF, and Ki67 are the most commonly used markers to identify CSCs in lung cancer." (PMID 36142766, 2022). "However, a correlation analysis between expression levels of CD276 (B7-H3) and FASN exhibited a positive correlation with poor prognosis in clinical lung cancer tissues." (PMID 33194695, 2020).
pancreatic cancer (79 papers, 2009 to 2026). "In a study of 150 patients with pancreatic cancer using immunohistochemistry, 66% of patients had positive CD276 staining, and high tumor CD276 expression was independently associated with poor survival." (PMID 38978106, 2024). "Recent studies have revealed that CD276 is significantly upregulated in pancreatic cancer, and high CD276 expression in patients is associated with a poor prognosis." (PMID 37974070, 2023). "CD276 also retained high expression in pancreatic cancer and was associated with worse OS." (PMID 36003146, 2022). "Further studies are needed to clarify the relationship between CD276 and pancreatic cancer progression." (PMID 40214484, 2025). "In summary, we reported on a CAR-T cell directed at CD276 that showed strong activity against pancreatic cancer cells in vitro and in vivo." (PMID 38978106, 2024). "A soluble form of CD276 is produced by monocytes, activated T cells, dendritic cells, and B7-H3-positive cancer cells, including human pancreatic cancer cells 13,14." (PMID 38902359, 2024). "CD276 dash CAR-T demonstrated enhanced pancreatic tumor control and improved expansion ability compared with conventional CAR-T in vivo." (PMID 38978106, 2024). "The result is important because it indicates that rapidly-manufactured CAR-T targeting CD276 for pancreatic cancer is feasible and promising by providing precise functional validation in preclinical studies." (PMID 38978106, 2024). "In this study, we proved CD276 CAR-T exhibited powerful activity against pancreatic cancer cells in vitro and in vivo." (PMID 38978106, 2024). "To further evaluate the anti-tumor efficacy of CD276 Dash CAR-T on pancreatic cancer in physiological environment, we constructed a NOG mouse xenograft model with subcutaneous injection of Capan-1 cells." (PMID 38978106, 2024). "Here we report on the preclinical characterization of a mAb directed to the target antigen B7-H3 (CD276) containing an Fc part with the amino acid substitutions S239D/I332E to increase affinity for CD16 (B7-H3-SDIE) for the treatment of pancreatic cancer." (PMID 38322253, 2024). "Here, we first tested CD276 antigen expression by flow cytometry and found pancreatic cancer cell lines showed positive expression of CD276 while hematologic tumor cell line like Reh and HL60 exhibited negative expression of CD276." (PMID 38978106, 2024). "In vivo xenograft mouse model, CD276 Dash CAR-T showed enhanced anti-pancreatic cancer efficacy and T cell expansion." (PMID 38978106, 2024). "CD276 CAR-T was highly effective against multiple pancreatic cancer cell lines at different E: T ratio while the killing efficiency was low in eradicating hematologic tumor cell lines, indicating a CD276-specific cytotoxicity." (PMID 38978106, 2024). "COL10A1 was transiently knocked down, while CD276 was transiently overexpressed in pancreatic cancer cells." (PMID 37974070, 2023). "Recent studies have revealed that high CD276 expression is independently correlated with poor pathological differentiation status, lymph node metastasis, and poor survival in pancreatic cancer patients." (PMID 37974070, 2023). "CD73, CD252, and CD276 were upregulated in pancreatic cancer compared to normal tissues by GEPIA2 analysis." (PMID 37835536, 2023). "In pancreatic cancer, CD276 expression was high, and patients with high CD276 expression had a poor prognosis." (PMID 37974070, 2023). "According to the results, knockdown of COL10A1 repressed CD276 expression in pancreatic cancer cells." (PMID 37974070, 2023). "Collectively, the results of our study indicate that COL10A1 facilitates tumour progression by upregulating CD276 in pancreatic cancer." (PMID 37974070, 2023). "Regarding immune inhibitors, IDO-1 regulates the immune response via NF-κB; CD276 can help promote pancreatic carcinoma metastasis and infiltration by activating the TLR4–NF-κB signaling pathway, via upregulated expression of IL-8 and VEGF." (PMID 34367975, 2021).
pancreatic cancer (continued). "CD276 can also help promote pancreatic carcinoma metastasis and infiltration by activating the TLR4–NF-κB signaling pathway, via upregulated expression of IL-8 and VEGF." (PMID 34367975, 2021). "High CD276 expression levels were already linked to poor prognosis in CLL and prostate and pancreatic cancer." (PMID 32188505, 2020). "Soluble CD276 promotes the invasion of pancreatic cancer cells via the NF-kappaB pathway." (PMID 38902359, 2024). "Therefore, the safety and efficacy of CD276 Dash CAR-T in pancreatic cancer patients need to be further explored in the future." (PMID 38978106, 2024). "This serves as a reminder that CD276 inhibitors alone or combined with PD-1 inhibitors may be a new direction for pancreatic cancer therapy." (PMID 37974070, 2023). "In the present study, we developed CD276 Dash CAR-T manufactured with less time and presented evidence that Dash CAR-T exhibited higher stemness and enhanced pancreatic tumor control compared to conventional CAR-T in vitro and in vivo." (PMID 38978106, 2024). "Here, we investigated the efficacy of CD276 CAR-T and rapidly-manufactured CAR-T against pancreatic cancer." (PMID 38978106, 2024). "Here, in a solid tumor-bearing mouse model, we found that both CD276-targeted conventional CAR-T and Dash CAR-T exhibited remarkable pancreatic cancer-control ability." (PMID 38978106, 2024). "In another study of 59 patients with pancreatic cancer, CD276 was found to be highly expressed in most pancreatic cancer tissues and significantly higher than in non-cancerous tissues or normal pancreas." (PMID 38978106, 2024). "Nevertheless, we validated the anti-tumor effects of CD276 CAR-T and Dash CAR-T against pancreatic cancer in preclinical studies and demonstrated that CD276 Dash CAR-T may be a potential treatment for pancreatic cancer patients." (PMID 38978106, 2024). "Here we found that CD276 CAR-T could efficiently kill multiple tumor cells in vitro and eradicate pancreatic cancer cells in vivo." (PMID 38978106, 2024). "In another study, CD276 expression by cancer tissue was higher than that by non-cancer tissue in each of 11 pancreatic cancer patients." (PMID 38902359, 2024). "Therefore, mounting evidence proved that CD276 has emerged as a promising therapeutic target for CAR-T therapy against solid cancers, including pancreatic cancer." (PMID 38978106, 2024).
non-small cell lung carcinoma (71 papers, 2009 to 2026). A group of at least three distinct histological types of lung cancer, including non-small cell squamous cell carcinoma, adenocarcinoma, and large cell carcinoma. "Previous research has shown that CD276 helps tumor cells evade the immune system in non-small cell lung cancer by collaborating with Tregs48." (PMID 38177255, 2024). "PD-L1 and CD276 blockade enhanced the antitumour response in non-small cell lung cancers expressing CD276." (PMID 37974070, 2023). "CD276 expression was responsible for the poor response to anti-PD-1 immunotherapy in non-small cell lung cancer and ovarian cancer." (PMID 36685583, 2022). "Studies have found that CD276 is expressed at both transcriptional and translational levels in six different non-small cell lung cancer cell lines." (PMID 31737785, 2019). "The oncogenic activities of CD276 have been reported in many human cancers, including acute monocytic leukemia, non-small cell lung cancer, gastrointestinal carcinoma, and mantle cell lymphoma." (PMID 27329595, 2016). "CD276 has been widely studied in non-small cell lung cancer (NSCLC)." (PMID 37373167, 2023). "CD276 was first derived from dendritic cells and the immune checkpoint in cancers; it impaired T cell–mediated anticancer immunity in ovarian cancer and destroyed the anti-PD-1 therapy in non-small cell lung cancer." (PMID 36226072, 2022). "The expression and significance of CD276 in non-small cell lung cancer (NSCLC) was explored." (PMID 31737785, 2019). "Another study found that the combination of CD276 inhibitors and PD-1 inhibitors was a promising treatment for non-small cell lung cancer that did not react to PD-1 inhibitors but expressed CD276." (PMID 37974070, 2023).
osteosarcoma (70 papers, 2013 to 2026). A usually aggressive malignant bone-forming mesenchymal neoplasm, predominantly affecting adolescents and young adults. "Immune checkpoint analysis of CD270 (HVEM), CD274 (PD-L1), and CD276 (B7H3) showed higher expression levels in metastases compared to the parental osteosarcomas, with CD274 as well as CD276 also being associated with poorer patient survival." (PMID 37048099, 2023). "B7-H3 (CD276) is overexpressed in osteosarcoma and plays a significant role in immune evasion." (PMID 40170852, 2025). "However, newer checkpoint molecules such as LAG-3, TIM-3, T cell immunoreceptor with Ig and ITIM domains (TIGIT), V-domain Ig suppressor of T cell activation (VISTA), and B7-H3 (CD276) have gained increasing attention as potential targets in osteosarcoma." (PMID 40170852, 2025). "B7-H3 (CD276) CAR T cells are also being tested for the treatment of osteosarcoma." (PMID 37569894, 2023). "CAR T-cells targeting B7-H3 (CD276), a checkpoint molecule highly expressed on pediatric solid tumor and brain tumors, have been generated for use in preclinical orthotopic xenograft models of osteosarcoma, Ewing sarcoma, and medulloblastoma." (PMID 33659929, 2021). "Surprisingly, CD276 expression in D-17 cells originating from an OS metastasis was inferior to those observed in COS cells, which were isolated from parental osteosarcomas." (PMID 37048099, 2023). "CD276 is expressed at high levels in a large proportion of human malignancies, including the pediatric solid tumors RMS, osteosarcoma, intrinsic pontine glioma, medulloblastoma, and Ewing sarcoma." (PMID 37924157, 2023). "Their target is the immune checkpoint molecule B7-H3 (CD276), a tumor antigen that is significantly upregulated in osteosarcoma." (PMID 36232719, 2022).